MDK (midkine)
Diseases named in the same sentence as MDK in open-access papers (continued):
Sharing a sentence is not in itself a finding about the gene and the disease.
Cachexia (3 papers, 2010 to 2023). Severe weight loss, wasting of muscle, loss of appetite, and general debility related to a chronic disease. "Our results provide evidence for an association of midkine and VEGF with systemic inflammation and malnutrition, supporting a possible involvement of these cytokines in the pathogenesis of cachexia." (PMID 20920199, 2010). "Previous studies concerning cachexia in gastrointestinal cancer revealed that other pro-inflammatory cytokines, such as IL-8 and, probably, vascular endothelial growth factor-A (VEGF-A) and midkine, might be involved in the process of cachexia." (PMID 20920199, 2010). "Midkine was related to inflammation and was correlated with albumin concentration, while the associations were not affected by cachexia." (PMID 20920199, 2010).
Cerebral ischemia (3 papers, 2015 to 2019). Restriction of arterial blood supply to the brain associated with insufficient oxygenation to support the metabolic requirements of the tissue. "For example, Midkine promotes functional recovery after spinal cord injury in rats, and in Mdk knockout mice, the time course of recovery from cerebral ischemia or peripheral nerve injury is delayed." (PMID 25803551, 2015).
cholangiocarcinoma (3 papers, 2018 to 2022). A carcinoma that arises from the intrahepatic biliary tree (intrahepatic cholangiocarcinoma) or from the junction, or adjacent to the junction, of the right and left hepatic ducts (hilar cholangiocarcinoma). "Our analysis suggests that expression of DEPDC1, FUT4, MDK, PACS1, PIWIL4, miR-22, miR-551b, and DNA methylation of cg27362525 and cg26597242 could be explored further as potential biomarkers of cholangiocarcinoma." (PMID 33193605, 2020).
chronic heart failure (3 papers, 2017 to 2020). "Of particular interest, serum MDK is elevated in adults with chronic heart failure and higher circulating MDK is associated with worse cardiac function." (PMID 28920060, 2017). "In adults with chronic heart failure (HF), circulating MDK is significantly upregulated and high-circulating MDK is associated with cardiac events and higher New York Heart Association (NYHA) functional classification." (PMID 28920060, 2017). "Although midkine upregulation has been demonstrated as a predictive marker for poor outcomes in patients with cancer and chronic heart failure, the cell proliferative effects of midkine does not always promote pulmonary arterial remodeling in these patients." (PMID 32587339, 2020).
Cirrhosis (3 papers, 2016 to 2024). A chronic disorder of the liver in which liver tissue becomes scarred and is partially replaced by regenerative nodules and fibrotic tissue resulting in loss of liver function. "However, MDK could differentiate NASH-related HCC from cirrhosis." (PMID 38247828, 2024). "They found elevated MDK levels in HCC patients compared with cirrhotic patients, suggesting MDK’s potential as a distinctive marker in HCC diagnosis and its differentiation from cirrhosis." (PMID 38247828, 2024). "GP73, MDK and DKK-1 proteins were assessed in 238 individuals divided into 4 groups (HCC, chronic HCV, and chronic HCV with cirrhosis and healthy subjects as a control) Serum levels of GP73, MDK, and DKK-1 were assessed in all subjects by ELISA." (PMID 32198440, 2020). "We assessed the performance of serum MDK, OPN, DKK1 and AFP alone or in combination for the diagnosis of HCC, as compared to their serum levels in patients with cirrhosis, chronic liver disease or healthy controls." (PMID 27219517, 2016). "Serum levels of MDK and OPN were higher in HCC patients compared to cirrhosis, CLD and HC groups." (PMID 27219517, 2016). "Interestingly, when NASH-related HCC was compared to NASH cirrhosis, MDK had a greater AUROC (0.86; 95% CI 0.72–1.0) compared to AFP (0.76; 95% CI 0.58–0.95) and OPN (0.66; 95% CI 0.44–0.88), suggesting that MDK may have a role in the diagnosis of NASH-related HCC." (PMID 27219517, 2016). "MDK was higher in the HCC group compared with other groups and could distinguish between HCC and non-HCC cases, despite the presence of cirrhosis." (PMID 38247828, 2024). "Likewise, MDK exhibited the capacity to successfully distinguish between HCC and non-HCC cases, despite the presence of cirrhosis." (PMID 38247828, 2024).
head and neck squamous cell carcinoma (3 papers, 2016 to 2023). A squamous cell carcinoma that arises from any of the following anatomic sites: lip and oral cavity, nasal cavity, paranasal sinuses, pharynx, larynx, and salivary glands. "In head and neck squamous cell carcinoma, the following markers have been studied: NFκB-p50, IκB, and the growth factor midkine by blood sampling, and total salivary protein combined with soluble CD44 levels (solCD44) in saliva." (PMID 32670885, 2020).
leukemia (3 papers, 2020 to 2025). A malignant (clonal) hematologic disorder, involving hematopoietic stem cells and characterized by the presence of primitive or atypical myeloid or lymphoid cells in the bone marrow and the blood. "Other hits in the experiment were soluble proteins as midkine, a heparin-binding growth factor that is overexpressed in many tumors and leukemia." (PMID 32575403, 2020). "NKL cells are a leukemia cell line, thereby proteins as midkine might be strongly expressed and potentially bound as peptides to HLA-G." (PMID 32575403, 2020). "Interestingly, MDK, which is involved in cell migration and growth, was downregulated by SOX11 knockdown in leukemia cell lines here and in an MCL cell line Z13816." (PMID 32029838, 2020).
metastatic tumor (3 papers, 2025). "Previous studies discussed additional key factors that led to the stabilization and increased expression of HIF1α in primary and metastatic tumors, such as midkine or LDHA." (PMID 40806669, 2025).
multiple sclerosis (3 papers, 2023 to 2025). A progressive autoimmune disorder affecting the central nervous system resulting in demyelination. "A study reported that patients recently diagnosed with Multiple Sclerosis (MS) and Neuromyelitis Optica exhibited higher MDK levels compared to healthy individuals." (PMID 40500394, 2025). "During development of experimental autoimmune encephalomyelitis (EAE), a preclinical animal model of Multiple Sclerosis (MS), T helper (TH) cells have been identified as MDK producer cells." (PMID 38098484, 2023). "A group has used MDK RNA aptamers, demonstrating that it induced T regulatory cell expansion and prevented autoimmune diseases such as multiple sclerosis." (PMID 37240085, 2023). "In the case of cancer, multiple sclerosis, ischemia, and other inflammation and neural diseases, MDK is a cytokine responsible for survival and proliferation in all of these conditions." (PMID 37240085, 2023). "By facilitating the migration of immune cells such as neutrophils and macrophages into affected tissues, MDK contributes to inflammation-induced tissue damage observed in conditions like multiple sclerosis, inflammatory bowel disease, and traumatic brain injury." (PMID 40500394, 2025).
psoriasis (3 papers, 2025). An autoimmune condition characterized by red, well-delineated plaques with silvery scales that are usually on the extensor surfaces and scalp. "When treating these four subpopulations as receptor sources, subsequent pathway analysis indicated that the communication networks in psoriasis encompassed several key immune and signaling pathways, including IL - 17, CXCL, midkine (MK), IL - 6, NOTCH, EGF, and MHC-II." (PMID 40959079, 2025). "Midkine is a heparin-binding growth factor broadly expressed in inflammatory diseases; recent studies have shown that MK regulates VEGF-A expression via the Notch2/HES1/JAK2-STAT5A signaling pathway, thereby exerting critical effects on angiogenesis in psoriasis." (PMID 40959079, 2025).
acute kidney injury (2 papers, 2015 to 2026). Sudden and sustained deterioration of the kidney function characterized by decreased glomerular filtration rate, increased serum creatinine or oliguria. "A brief, learning‐evoked hippocampal pulse of MDK (<24 h) enhances memory, yet prolonged systemic exposure in maladaptive repair after acute kidney injury does the opposite." (PMID 41276912, 2026). "We tested the hypothesis whether midkine could represent an early biomarker of contrast-induced acute kidney injury (CIAKI) in 89 patients with normal serum creatinine undergoing PCI." (PMID 25629054, 2015). "As tubular injury, due to direct cytotoxic effects or in association with the generation of oxygen free radicals, contributes to contrast nephropathy, we hypothesized that midkine may serve as a potential marker of acute kidney injury." (PMID 25629054, 2015).
acute lymphoblastic leukemia (2 papers, 2023 to 2025). Leukemia with an acute onset, characterized by the presence of lymphoblasts in the bone marrow and the peripheral blood. "High MDK expression has also been associated with enhanced drug efflux capacity in childhood acute lymphoblastic leukemia (ALL), suggesting a role in multidrug resistance (MDR)." (PMID 40500394, 2025). "In lymphoblastic leukemia cells, MDK overexpression enhanced the efflux of chemotherapeutic agents, contributing to multidrug resistance." (PMID 40500394, 2025).
acute respiratory distress syndrome (2 papers, 2017 to 2020). Progressive and life-threatening pulmonary distress in the absence of an underlying pulmonary condition, usually following major trauma or surgery. "Plasma concentration of Midkine dramatically increased in patients with acute respiratory distress syndrome (ARDS; Zhang and Baker, 2017)." (PMID 33414726, 2020).
anemia (2 papers, 2020 to 2026). A reduction in the number of red blood cells, the amount of hemoglobin, and/or the volume of packed red blood cells. "Finally, they concluded that UC was clearly associated with increased circulating MDK, which corresponds with clinical, endoscopic, inflammatory, and angiogenic activity, and with anemia." (PMID 31905498, 2020). "MDK gene expression was inversely related to ESR level and positively correlated to serum level of MDK and anemia occurrence." (PMID 42149205, 2026).
Anxiety (2 papers, 2014 to 2023). Intense feelings of nervousness, tension, or panic often arise in response to interpersonal stresses. "Disruption of either PTN or the homologous protein midkine has been associated with heightened anxiety in mice." (PMID 25000129, 2014). "Moreover, some significant genes within these nominally significant overlapping pathways have been previously associated with pain problems and/or anxiety symptoms (e.g., the ZNRD1 gene; the MDK gene; the FOXO3 gene; the COMT gene; the NFATC4 gene)." (PMID 37146008, 2023).
bladder tumor (2 papers, 2021 to 2024). "Midkine (MDK, encoded by MDK) is an enhancer of angiogenesis, and MDK expression has been shown to be positively correlated with vascular density in bladder tumors." (PMID 34428745, 2021). "Midkine (MDK) is a heparin-binding growth factor that is overexpressed in bladder tumor tissue and urine from BC patients when compared to healthy individuals." (PMID 39184050, 2024).
cardiac hypertrophy (2 papers, 2017 to 2021). "The knockout of the midkine gene inhibited neutrophil infiltration and reduced myocardial hypertrophy induced by subtotal nephrectomy compared with wild-type mice." (PMID 33680285, 2021). "After TAC, compared with wild-type mice, transgenic mice with cardiac-specific overexpression of midkine showed more severe cardiac hypertrophy and dysfunction and a lower survival rate." (PMID 33680285, 2021). "In MDK KO mice with subtotal nephrectomy, absence of MDK led to decreased cardiac hypertrophy due to reduced phosphorylation of cardiac epidermal growth factor receptor." (PMID 28920060, 2017).
cardiac ischemia (2 papers, 2017 to 2023). "MDK has also been linked to ischemic injury in several other tissues; therefore, it is logical to investigate the role of MDK in cardiac ischemia/reperfusion (I/R) injury." (PMID 28920060, 2017). "Upon renal ischemia-reperfusion, a process frequently leading to excessive tissue injury and destructive inflammatory responses, MDK promotes the migration of neutrophils and macrophages to the site of injury while in cardiac ischemia-reperfusion injury MDK prevents myocardial apoptosis." (PMID 38098484, 2023).
cerebral infarct (2 papers, 2008 to 2015). "Indeed, it was demonstrated that the neurotrophic factor midkine (MK), which could delay the process of neuronal death during the early phase after cerebral infarction, was higher expressed in the cells of the peri-infarct region after physical training program." (PMID 26682073, 2015).
Cognitive impairment (2 papers, 2016 to 2026). Abnormal cognition is characterized by deficits in thinking, reasoning, or remembering. "In our study, we observed an elevation in MDK levels in the serum and hippocampus of mice subjected to post‐ischemic renal injury, suggesting that MDK could serve not only as a biomarker for kidney injury but also may be implicated in cognitive impairment." (PMID 41276912, 2026). "The current study offers a comprehensive exploration of the role of MDK in mediating cognitive impairment and microglial activation in AKI." (PMID 41276912, 2026). "Furthermore, our study demonstrates that inhibiting renal MDK expression alleviates cognitive impairment and reduces microglial activation, highlighting the therapeutic potential of targeting the MDK‐LRP1 pathway in AKI‐related cognitive decline." (PMID 41276912, 2026). "This elevation in MDK correlates with an increase in activated microglia in the hippocampus and an upregulation of P2ry12 expression, suggesting a potential link between MDK, microglial activation, and cognitive deficits after ischemic renal injury." (PMID 41276912, 2026). "However, it remains unclear whether MDK drives secondary cognitive impairment after ischemic renal injury." (PMID 41276912, 2026). "To determine how renal MDK expression contributes to cognitive impairment following AKI, we locally injected adenoviruses carrying MDK‐shRNA (MDK‐shRNA) and a control vector virus (Vector) into the kidneys of mice, followed by the induction of IRI." (PMID 41276912, 2026).
differentiated thyroid carcinoma (2 papers, 2017 to 2024). Differentiated thyroid carcinoma (DTC), also known as papillary or follicular thyroid carcinoma, is a slow-growing malignancy usually presenting in adults as an asymptomatic thyroid mass. "The latest study found that Midkine/free thyroxine (MK/FT4) and Midkine/thyroglobulin (MK/TG) in FNA washing fluid have diagnostic value for papillary thyroid carcinoma, especially thyroid nodules with uncertain cytology." (PMID 37608676, 2024).
dilated cardiomyopathy (2 papers, 2020 to 2025). Cardiomyopathy which is characterized by dilation and contractile dysfunction of the left and right ventricles. "In the context of dilated cardiomyopathy (DCM), a study by Danielle Jeffrey indicated that midkine is up-regulated in both the plasma and cardiac tissue of pediatric patients with DCM." (PMID 40002917, 2025).
endometriosis (2 papers, 2019 to 2025). The growth of functional endometrial tissue in anatomic sites outside the uterine body. "Multiple correlations were found between analytes concentrations in EC and endometriosis groups, whereas only one pair of markers (kallikrein-6/midkine) were correlated in control group." (PMID 31035965, 2019). "This aligns with previous evidence of elevated MDK in endometriosis." (PMID 40429950, 2025). "Concentration of seven analytes (ALDH1A, CA9, CD44, hepsin, midkine, TGM2, and kallikrein-6) differed in endometriosis samples as compared to control samples and levels of five markers (ALDH1A, CA9, CD44, hepsin, and midkine) were different between endometriosis and EC samples." (PMID 31035965, 2019). "Significant differences were encountered between endometriosis and EC in case of five analytes, of which all were increased: ALDH1A (p = 0.019), CA9 (p = 0.031), CD44 (p = 0.010), hepsin (p = 0.007), midkine (p < 0.001)." (PMID 31035965, 2019).
experimental autoimmune encephalomyelitis (2 papers, 2015 to 2025). An autoimmune demyelinating disease of the central nervous system that is produced experimentally in animals by the injection of homogenized brain or spinal cord in Freund's adjuvant. "Moreover, in a mouse model of experimental autoimmune encephalomyelitis, infiltration of inflammatory cells into the spinal cord was decreased in MDK-deficient mice compared to WT mice." (PMID 40943439, 2025).
Hepatitis (2 papers, 2020 to 2023). Inflammation of the liver. "Recent studies have shown that other proteins could also be used as sensitive and specific markers for hepatitis as well as for HCC including the Golgi protein 73 (GP73); which is also named Golgi phosphoprotein 2 “GOLPH2, the Dickkopf-1(DKKpf-1 or DKK-1), and Midkine (MDK)." (PMID 32198440, 2020).
ischemic stroke (2 papers, 2019 to 2023). A stroke disorder caused by obstruction of blood flow to the brain, due to thrombotic (local blood clot formation) or embolic (due to a blood clot or other material traveling from another site) event. "Furthermore, 3 weeks of daily 30 min exercise sessions before ischemic stroke promotes angiogenesis, increases brain-derived neurotrophic factor and midkine expression, reduces infarct volumes, neuronal apoptosis, and oxidative damage, and improves motor function but not neurological function." (PMID 30941660, 2019).
liver disease (2 papers, 2016 to 2021). "On the other hand, however, midkine is a powerful chemoattractant for neutrophils, which are of particular importance in the pathogenesis of liver diseases." (PMID 34439416, 2021). "We have shown in the cross-sectional study that serum MDK could have a diagnostic role in AFP-negative HCC and may differentiate NASH-HCC from non-malignant liver disease." (PMID 27219517, 2016).
malignant pleural mesothelioma (2 papers, 2017 to 2024). A malignant neoplasm that arises from mesothelial cells in the pleura and shows a diffuse growth pattern. "We evaluated possible diagnostic and prognostic values of serum midkine in malignant pleural mesothelioma in comparison with those of serum mesothelin, a well-established diagnostic biomarker." (PMID 28335760, 2017). "We investigated in the present study to compare mesothelin, a well-established biomarker for mesothelioma, with midkine, a possible novel marker, in the diagnosis and the prognosis of malignant pleural mesothelioma." (PMID 28335760, 2017).